GLUD2 (glutamate dehydrogenase 2)
Description:
Important for recycling the chief excitatory neurotransmitter, glutamate, during neurotransmission.
Synonyms: GLUDP1; GDH2
Tractability: PROTAC: ubiquitination databases record sites on it.
Gene: Protein-coding gene on chromosome X (121,047,610 to 121,050,094, forward strand). Ensembl gene ENSG00000182890.
Subcellular location: Mitochondrion matrix
Subcellular location (Human Protein Atlas): Mitochondria
Pathways (Reactome):
Metabolism: Glutamate and glutamine metabolism
Organelle biogenesis and maintenance: Transcriptional activation of mitochondrial biogenesis
Gene Ontology:
Molecular function: ADP binding; glutamate dehydrogenase (NAD+) activity; glutamate dehydrogenase [NAD(P)+] activity; GTP binding; L-leucine binding; protein binding; glutamate dehydrogenase (NADP+) activity; oxidoreductase activity; oxidoreductase activity, acting on the CH-NH2 group of donors, NAD or NADP as acceptor
Biological process: glutamate metabolic process; L-glutamate biosynthetic process; L-glutamate catabolic process; amino acid metabolic process
Cellular component: cytosol; mitochondrion; mitochondrial matrix
Homologues: Orthologues: mouse Glud1 (94% identical), rat Glud1 (93% identical), dog GLUD1 (93% identical), pig GLUD1 (91% identical), tropical clawed frog glud1 (83% identical), zebrafish glud1a (81% identical), Drosophila melanogaster Gdh (67% identical), Caenorhabditis elegans gdh-1 (58% identical), Drosophila melanogaster bb8 (44% identical). Paralogues in human: GLUD1 (96% identical).
Diseases named in the same sentence as GLUD2 in open-access papers:
GLUD2 is named in the same sentence as 34 diseases in open-access papers, as found by Europe PMC text mining. Sharing a sentence is not in itself a finding about the gene and the disease. The quoted sentences say what the papers report.
glioma (12 papers, 2017 to 2024). A benign or malignant brain and spinal cord tumor that arises from glial cells (astrocytes, oligodendrocytes, ependymal cells). "Conversely, the overexpression of glutamate dehydrogenase 2 (GLUD2) rescues the growth-inhibitory effect of IDH1 mutation in murine glioma progenitor cells." (PMID 37108511, 2023). "Glutamate dehydrogenase 2 (GLUD2) also could compensate to synthesize α-KG in IDH1mut gliomas, thereby resisting the growth inhibition caused by IDH1 mutation." (PMID 33472598, 2021). "Moreover, studies in glioma cells with the R132H IDH1 mutation revealed that selective inhibition of GLUD2 expression markedly slows cell growth." (PMID 28208702, 2017). "Indeed gene expression profiling revealed that GLUD1 and GLUD2 that generate α-ketoglutarate via glutamate oxidation, are selectively and consistently up-regulated in glioma cells harboring IDH mutations." (PMID 28208702, 2017). "The maximal GLUD2 effects were found during early post-natal development, suggesting the possibility that GLUD2 expression may support lipid biosynthesis through hGDH2-linked oxidative generation of citrate as originally suggested for glioma cells." (PMID 28208702, 2017). "The development of IDH-mutant gliomas has also been demonstrated to be furthered by the production of the glutamate dehydrogenase 2 (GLUD2) protein." (PMID 39329757, 2024). "As IDH-mutant gliomas occur in the prefrontal cortex as well, GLUD2 upregulation provides degradation of the large amount of glutamate to produce α-KG and for biosynthesis of other vital molecules, which is critical for the growth of IDH-mutant cells." (PMID 34356864, 2021). "Here, we found that mutated GLUD2 decreased EAAT1 and EAAT2 expression and reduced glutamate uptake in the SN of MPTP-treated mice and the MPP+-treated glioma cell line U251." (PMID 33093440, 2020). "Indeed, knockdown of the GLUD2 gene indicates that the gene is required for the glutamate-dependent growth of glioma." (PMID 38673928, 2024). "For example, IDH1mut gliomas may adjust for the depletion of TCA intermediates by upregulating glutamate dehydrogenase 2 expression." (PMID 35134075, 2022). "Moreover, increased expression of nerve-tissue-specific GLUD2 leads to enhanced tumor growth in mutIDH1R132H glioma murine models." (PMID 35028610, 2021). "In contrast to the previous notion presenting GLUD2 as an enzyme promoting the growth of at least some glioma cells, these results suggest that in some glioma cell types, an enhancement of GLUD2 activity could result in blocked/reduced proliferation." (PMID 32013066, 2020). "A specific human isoform of glutamate dehydrogenase 2 (GDH2) was also reported to promote glioma." (PMID 31847543, 2020). "However, the role of GLUD2 in glioma pathogenesis appears to be more complex and may be context specific." (PMID 32013066, 2020). "Glioma studies have discovered that GLUD2 expression promotes cell growth and metabolite flux to lipids in IDH1R132H glioma progenitors in mice." (PMID 38673928, 2024). "MutIDH1 glioma cells are likely reliant on GLUD2 for glutamate-dependent anaplerosis of the TCA cycle and express GLUD2 at significantly higher levels than WT IDH1 glioma." (PMID 35028610, 2021). "That is, R132H mutation, which disrupts normal function of isocitrate dehydrogenase IDH1, negatively affects the growth of glioma progenitor cells, but genetically induced expression of human GLUD2 but not GLUD1 rescues the cells." (PMID 38673928, 2024). "Glutamate dehydrogenase 1 (GLUD1) and GLUD2, which catalyze oxidative deamination of glutamate to 2-OG, are significantly elevated in mutIDH1R132H glioma compared with WT IDH1 glioma, indicating the potential for increased glutamate utilization by the TCA cycle." (PMID 35028610, 2021). "Expression of human GLUD1 did not promote the growth of IDH1R132H murine glioma progenitors, but GLUD2 rescued the growth of these cultures." (PMID 32013066, 2020).
glioma (continued). "Taken together, these results revealed that GLUD2 promotes the growth of IDH1R132H glioma cells in a manner that is not duplicated by overexpression of GLUD1." (PMID 32013066, 2020). "Conversely, expression of GLUD2 (but not GLUD1) promotes tumor expansion, suggesting that R132H IDH1 glioma cells proliferate by utilizing enhanced glutamate flux through the GLUD2 pathway." (PMID 28208702, 2017).
Ataxia (8 papers, 2018 to 2024). Ataxia refers to impaired coordination of voluntary muscle movement. "In the case of the PF synapse, a deficit in the formation or stabilization, as in GluD2 or mGlu1 receptor mutants, is sufficient to cause a few motor symptoms related to ataxia." (PMID 29760657, 2018). "Mutations in the GRID2 gene encoding for GluD2 have been recently associated with cerebellar ataxia in several patients." (PMID 29760657, 2018). "Both the GluD2-A654T (lurcher) mutation and patient variants such as A654D, L656V, and T649A share similar constitutive activity, as observed in our voltage clamp studies, and they also share the phenotype of cerebellar ataxia." (PMID 37944084, 2024). "Associated with GluD2, an old mutant mouse Lurcher is characterized by ataxia." (PMID 35326323, 2022). "For example, GluD2 mutations have been shown in cases of congenital cerebellar ataxia in patients." (PMID 30979012, 2019). "GluD2 knockout (KO) mouse models have demonstrated a prominent motor dyscoordination and cerebellar ataxia." (PMID 30979012, 2019). "Furthermore, Cbln1 and GluD2 play relevant roles in motor coordination and learning, while deficits lead to motor impairment, such as ataxia in mouse models." (PMID 30979012, 2019). "A better understanding of the involvement of Stau2 in GluD2-dependent synapse formation could therefore provide new therapeutic options for cerebellar ataxia and similar disorders." (PMID 30979012, 2019). "The link between GluD2 and ataxia is strongly supported by several studies in mice with different mutations in the Grid2 gene, that have provided important information about the role of the GluD2 receptor in cerebellar functions and how their mutations affect cerebellar circuitry and cause ataxia." (PMID 29760657, 2018). "Whether such modulators would be directly relevant to pharmacotherapy is unclear, as the links between low GluD1 expression and schizophrenia and GluD2 overactivity and cerebellar ataxia may pertain to early development (51, –53) and thus be inaccessible to pharmacotherapy." (PMID 38285949, 2024).
Parkinson disease (5 papers, 2016 to 2025). A progressive degenerative disorder of the central nervous system characterized by loss of dopamine producing neurons in the substantia nigra and the presence of Lewy bodies in the substantia nigra and locus coeruleus. "More attention should be paid to the genetic variants of GLUD1 and GLUD2 in patients with hyperinsulinism, inherited predisposition to diabetes, as well as Parkinson’s and Alzheimer’s diseases." (PMID 38673928, 2024). "In the GLUD2 gene, a relatively frequent polymorphism resulting in an S498A substitution is associated with Parkinson’s disease onset." (PMID 38673928, 2024). "Case 4 was also homozygous for variant rs9697983 [c.1492T>G, p.Ser498Ala] in the GLUD2 gene, associated with Parkinson's disease (OMIM#168600)." (PMID 33815474, 2021). "Notably, both GLUD2 and VDAC2 encoded proteins have oral involvement in salivary glands and are associated with Parkinson’s disease, emphasizing metabolic complexity and its connection to neurodegenerative disorders in salivary gland dysfunction." (PMID 40806170, 2025). "The link between the earlier onset of Parkinson’s disease and the S498A mutation was found in men but not in women, which can be explained by the location of the GLUD2 gene on the X chromosome." (PMID 38673928, 2024).
glioblastoma (3 papers, 2022). The most malignant astrocytic tumor (WHO grade IV). "The expression of glutamate dehydrogenase 2 (GLUD2) is associated with the histopathological classification, prognosis and survival of patients with glioblastoma." (PMID 36468004, 2022). "GLUD2 was downregulated in glioblastoma, and GLUD2 inhibited glioblastoma progression by promoting cell cycle arrest and leading to mitochondrial dysfunction." (PMID 36203437, 2022). "Glutamate dehydrogenase 2 (GLUD2) overexpression was found to inhibit glioblastoma cell growth." (PMID 35874811, 2022).
Cerebellar atrophy (2 papers, 2018 to 2024). Cerebellar atrophy is defined as a cerebellum with initially normal structures, in a posterior fossa with normal size, which displays enlarged fissures (interfolial spaces) in comparison to the foliae secondary to loss of tissue. "We expect that for gain-of-function constitutively active GluD2 variants, a small molecule capable of inhibiting the constitutive inward current could reduce excitotoxity of the Purkinje cells and possibly reduce cerebellar atrophy." (PMID 37944084, 2024).
autoimmune encephalitis (1 paper, 2018). Inflammation of the brain secondary to an immune response triggered by the body itself. "By contrast, in the control groups, only 5 of 139 (3.6%) of the pediatric neurologic controls had GluD2 antibodies (Rasmussen encephalitis 2/23, new-onset epilepsy 0/78, autoimmune encephalitis 3/38; p < 0.0001, Fisher exact test) (data available from Dryad, doi.org/10.5061/dryad.tq61224)." (PMID 30045961, 2018).
Bradycardia (1 paper, 2016). A slower than normal heart rate (in adults, slower than 60 beats per minute). "We conclude that the GluD2 mutation in the ho15J mice affects stable retention of the acquired conditioned bradycardia." (PMID 27820843, 2016). "In the present study, we show that fear-conditioned bradycardia responses could be acquired, expressed and extinguished in ho15J mice, a GluD2 mutant mouse similar to certain human patients." (PMID 27820843, 2016). "Therefore, we conclude that the GluD2 signaling pathway plays a crucial role in stable retention of the acquired conditioned bradycardia." (PMID 27820843, 2016). "Thus, the mutation of GluD2 in the ho15J mice did not affect the rate of extinction of conditioned bradycardia." (PMID 27820843, 2016).
colon cancer (1 paper, 2022). "We found that NLRP3 and GLUD2 were the most common necroptosis-related gene alteration in colon cancer patients." (PMID 35874811, 2022).
encephalitis (1 paper, 2018). An acute inflammatory process affecting the brain parenchyma. "Several single or small case reports have described antibodies to GluD2, and other glutamate-receptor subtypes, mainly in adult patients with cerebellitis and encephalitis." (PMID 30045961, 2018).
Hyperammonemia (1 paper, 2023). An increased concentration of ammonia in the blood. "A third pathway that would lead to hyperammonemia is through GLUD2, increased in FLC (log2 = 1.9), which makes glutamate into ammonia and 2-oxoglutarate." (PMID 37343102, 2023).
hyperinsulinism (1 paper, 2024). Abnormally high levels of insulin in the blood. "Thus, downregulation at the expression level is involved in the prevention of possible GLUD2-related hyperinsulinism." (PMID 38673928, 2024).
kidney cancer (1 paper, 2021). Primary or metastatic malignant neoplasm involving the kidney. "Additional examples among the core CT genes are CMTM1 (signaling molecule) and SLC1A6 (amino acid transporter), which are unfavorable expression markers for pancreatic and urothelial cancer, while KHDRBS3 (RNA splicing) and GLUD2 (glutamate dehydrogenase) are favorable markers for kidney cancer." (PMID 33426787, 2021).
neuroblastoma (1 paper, 2018). Neuroblastoma (NB) is the most common solid, extracranial childhood tumor. "The expression of GluD2 in neuroblastoma tissue taken from a GluD2 sera–positive patient with OMAS was confirmed by immunofluorescence." (PMID 30045961, 2018). "It is known that in this early period, GluD2 expression rises in the cerebellum, and concurrently, neuroblastomas, which we show can express GluD2, are also maturing." (PMID 30045961, 2018). "Also, a neuroblastoma from one of the GluD2-positive OMAS patients (OMAS 15) bound the commercial anti-GluD2 antibody indicating the presence of GluD2 within that tumor." (PMID 30045961, 2018). "Indeed, by linking GluD2, neuroblastomas, and the cerebellar nuclei, our data generate several hypotheses offering potential insights into OMAS etiology and pathogenicity." (PMID 30045961, 2018). "Third, GluD2 antibodies were not unique to children with OMAS but were also found in 2 of 4 children with neuroblastoma but without neurologic disease." (PMID 30045961, 2018). "In addition, 2 of the 4 (50%) sera from patients with neuroblastoma without neurologic features showed GluD2 antibodies." (PMID 30045961, 2018). "Antibodies to GluD2 were identified in 14/16 (87%) OMAS samples, compared with 5/139 (5%) pediatric and 1/38 (2.6%) adult serum controls (p < 0.0001), and in 2/4 sera from patients with neuroblastoma without neurologic features." (PMID 30045961, 2018).
transverse myelitis (1 paper, 2018). "By contrast, in one patient with transverse myelitis following allogenic stem cell transplantation, patient serum IgG stained both the cerebellar molecular layer and GluD2-transfected HEK cells." (PMID 30045961, 2018).
triple-negative breast carcinoma (1 paper, 2020). An invasive breast carcinoma which is negative for expression of estrogen receptor (ER), progesterone receptor (PR), and human epidermal growth factor receptor 2 (HER2). "RNA sequencing of triple-negative breast cancer samples has shown GLUD2 variant mutations." (PMID 32373524, 2020).
xerostomia (1 paper, 2025). Dryness of the mouth resulting from reduced salivary secretion. "Downregulation of Glutamate dehydrogenase 2 encoded by GLUD2 in submandibular glands observed in our study suggests additional metabolic dysregulation in xerostomia patients." (PMID 40806170, 2025). "The downregulation of key proteins involved in oxidative stress and neurodegenerative diseases, encoded by PARK7, GLO1, GLUD2, VDAC2, UQCRC1, and UNC5C, including the 20S proteasome core complex proteins, highlights a possible mechanistic link to xerostomia pathophysiology." (PMID 40806170, 2025).
tumor (5 papers, 2017 to 2022). "Furthermore, patients with proneural GBM, associated with the most favorable outcome, displayed higher levels of GLUD2 compared to the patients with the other tumor types." (PMID 32013066, 2020). "Antibodies to surface-expressed GluD2 could identify a therapy-responsive disorder that would benefit from early treatment and tumor surveillance." (PMID 30045961, 2018). "In an in vivo model, overexpression of GLUD2 completely abrogated the negative effect of IDH1R132H on tumor aggressiveness." (PMID 32013066, 2020).
cancer (4 papers, 2019 to 2023). A tumor composed of atypical neoplastic, often pleomorphic cells that invade other tissues. "The GLUD isoenzymes GLUD1 and GLUD2 are both increased in human malignancies, allowing cancer cells to employ this pathway for growth and proliferation." (PMID 37048450, 2023). "The conversion of glutamine to glutamate by glutaminase (GLS1 or GLS2), which is further transformed to α-ketoglutarate (α-KG) by glutamate dehydrogenase (GLUD1 or GLUD2) or aminotransferases, promotes the TCA metabolism that contributes to sustaining the energy used for cancer cell proliferation." (PMID 35054324, 2022).
neurologic disease (2 papers, 2018 to 2024). "This suggests a more localized intolerance to variation in this domain of GluD1 M3 compared to GluD2 and demonstrates a new functional mechanism by which GRID1 variants might trigger neurological disease." (PMID 37944084, 2024).
GLUD2 also shares sentences with these, for which no sentence is quoted: cerebellar ataxia (5 papers); Alzheimer disease (2); astrocytoma (2); schizophrenia (2); behavioral disorder (1); Brain atrophy (1); developmental delay (1); diabetes (1); dystrophinopathy (1); endometrial cancer (1); epileptic seizures (1); hepatoma (1); movement disorder (1); neurodegenerative disease (1); Parkinson’s (1).